CD200R1 (CD200 receptor 1)
Diseases named in the same sentence as CD200R1 in open-access papers (continued):
Sharing a sentence is not in itself a finding about the gene and the disease.
neurodegenerative disease (6 papers, 2016 to 2025). A disorder of the central nervous system characterized by gradual and progressive loss of neural tissue and neurologic function. "In neurodegenerative diseases, the function of these receptors is compromised, and levels of CD200 and CD200 receptor 1 (CD200R)—and the strength of their interaction—are markedly reduced." (PMID 41465422, 2025).
immune diseases (4 papers, 2014 to 2025). "We thus presume that the upregulated DEGs such as Cav1, CD200R1, TNFRSF17 and CXCR3 and downregulated DEGs such as EIF1AY and DDX3Y in healthy female may be involved in gender predominance of some immune diseases." (PMID 24741625, 2014). "Moreover, the upregulated DEGs (Cav1, CD200R1, TNFRSF17, and CXCR3) and downregulated DEGs (EIF1AY and DDX3Y) in healthy female may be involved in gender predominance of some immune diseases." (PMID 24741625, 2014).
brain diseases (2 papers, 2020 to 2021). "The interaction between CD200 and CD200R1 is critical for inhibiting microglial activation and localized neuroinflammation during the pathological development of several brain diseases, including Parkinson’s disease, optic nerve crush, and germinal matrix hemorrhage." (PMID 32473633, 2020).
bacterial infections (1 paper, 2019). "CD200R1 contributes to the resolution of neuroinflammation, uniquely impacts monocyte responses, and is an important regulator of the body’s peripheral immune response to bacterial infection." (PMID 30777093, 2019). "Given the role of CD200R1 in regulating T cell tolerance and systemic immune function, it is possible that CD200R1-KO mice are unable to mount the appropriate adaptive responses to mitigate the detrimental effects of spontaneous bacterial infections that are known to occur in the MCAO model." (PMID 30777093, 2019).
CD200R1 also shares sentences with these, for which no sentence is quoted: lung carcinoma (7 papers); leukemia (6); inflammatory bowel disease (5); endometriosis (4); hematologic malignancies (4); schizophrenia (4); acute myeloid leukemia (3); epilepsy (3); inflammation (3); allergic asthma (2); atherosclerosis (2); brain ischemia (2); cutaneous squamous cell carcinoma (2); dementia (2); Hypertension (2); immunodeficiencies (2); multiple myeloma (2); Obesity (2); pancreatic cancer (2); prion disease (2); sarcoidosis (2); Sepsis (2); abortion (1); acute respiratory distress syndrome (1); acute-on-chronic liver failure (1); adenocarcinoma (1); adenomyosis (1); age-related macular degeneration (1); androgenetic alopecia (1); antibody deficiencies (1).
A further 69 diseases each share a sentence with CD200R1 in 1 paper.